MMP8 (matrix metallopeptidase 8)
Diseases named in the same sentence as MMP8 in open-access papers (continued):
Sharing a sentence is not in itself a finding about the gene and the disease.
dental caries (9 papers, 2018 to 2025). The decay of a tooth, in which it becomes softened, discolored, and/or porous. "The causal relationship between caries and salivary MMP-8 has not been established, but the association between the number of cariotic lesions and MMP-8 levels suggests a role for the collagenase in the dentin caries process." (PMID 32143418, 2020). "The role of MMPs in dental caries and erosion has also been proposed, and inactivation of MMP-8 with chlorhexidine, FeSO4 and green tea has been shown to inhibit dental erosion development." (PMID 35448063, 2022). "The results showed that untreated dental caries were strongly correlated with elevated MMP-8 and MMP-9 salivary levels, and a positive relationship was observed for lesions affecting deciduous teeth." (PMID 35327715, 2022). "With reference to dental caries, a high positive correlation of MMP-8 with the number of teeth with active caries (D) in the mixed dentition group (JIA MD), so in the period of eruption of permanent teeth, was found." (PMID 31781639, 2019). "Hence, to throw more light on the role played by salivary MMPs, this study was conducted with a primary objective of estimating and correlating the salivary levels of MMP-8 and dental caries." (PMID 32071691, 2020). "Also, caries correlated strongly with salivary levels of MMP-8 suggesting the potential role of MMPs in the progression of dental caries." (PMID 32071691, 2020). "Some studies have indicated that dental caries has an impact on oral MMP-8 levels, and thereby, caries lesions may affect the outcome of oral rinse aMMP-8 PoC immunotests." (PMID 32143418, 2020). "MMP-1 (collagenase-1), MMP-2 and -9 (gelatinase-A and -B), MMP-3 (stromolysin-1), MMP-8 (collagenase-2) and MMP-20 (collagenase-3) are currently known to participate in dental caries and dental restoration failure." (PMID 36012195, 2022). "They found that human MMP-2, MMP-8, and MMP-9 were identified in demineralized dentinal lesions and inhibition of MMPs can reduce dentin caries progression." (PMID 29849633, 2018). "Several MMPs are reported in saliva apparently derived from salivary glands and gingival crevicular fluid out of which MMP-8 and MMP-9 are hypothesized as the abundant and predominant proteases in dentin caries especially in the outer layers of caries compared with the deep caries layer." (PMID 32071691, 2020).
Hypertension (9 papers, 2013 to 2025). The presence of chronic increased pressure in the systemic arterial system. "Our subgroup analysis was carried out to see if independent CVD risk factors such as age, BMI and a history of hypertension exerted significant influence on the extent of change in the levels of MMP-8, MMP-9 and TIMP-4 during the 5-year follow-up period." (PMID 32451401, 2020). "In patients with high blood pressure, an increased level of MMP-8 and lysozyme in saliva and an increase in the MMP-8/TIMP-1 ratio were observed." (PMID 31781639, 2019). "The mean value of MMP-8 was more than 50% higher in patients with one or several inflammatory conditions (heart disease, high blood pressure, bowel disease, and muscle and joint diseases)." (PMID 23637817, 2013). "Variable inflammation, which could include a combination of systemic conditions like heart disease, high blood pressure, bowel disease, and muscle and joint diseases, was associated with increased concentrations of IL-8, MMP-8, MMP-8/TIMP-1 ratio, lysozyme and total protein." (PMID 23637817, 2013). "MMP-8 concentration was lower and TIMP-1 higher in individuals with hypertension and in those with antihypertensive medication when compared to individuals with no measured hypertension and no antihypertensive medication (p < 0.001 for both proteins)." (PMID 39917664, 2024). "Patients reporting high blood pressure presented with higher concentrations of MMP-8 and lysozyme, as well as an increased MMP-8/TIMP-1 ratio but these differences were lost after compensation for age, gender and smoking habits." (PMID 23637817, 2013).
malaria (9 papers, 2011 to 2025). Malaria is a serious and sometimes fatal disease caused by a parasite that commonly infects a certain type of mosquito which feeds on humans. "In our analyses, IL1R2, LCN2, LTF, and MMP8 were associated with all SM subgroup comparisons to uncomplicated malaria." (PMID 40383794, 2025). "On the contrary, TIMP-1 is associated with signs and symptoms of severe malaria, and MMP-8 levels are elevated in patients with severe or uncomplicated P. falciparum malaria." (PMID 25436884, 2013). "Neutrophils may be involved in the development of complications associated with malaria by releasing toxic granules containing enzymes such as myeloperoxidase, neutrophil elastase, and matrix metalloproteinase-8 (MMP-8)." (PMID 39598252, 2024). "We have shown that mature blood‐stage malaria parasites, such as those sequestered in large numbers in the brain microvasculature in CM, can trigger release of MMP8 from neutrophils." (PMID 33968402, 2021). "This could explain the apparent paradox that systemic levels of MMP8 are generally similar in severe and uncomplicated malaria." (PMID 33968402, 2021). "In the light of these results, it may be argued that TIMP-1 and MMP-8 may predict the severity of malaria." (PMID 25436884, 2013). "It has been reported that the neutrophil granule proteins MMP8, OLFM4, DEFA3, and ELANE are increased in severe malaria versus uncomplicated malaria." (PMID 36380373, 2022). "Moreover, serum MMP-8 levels were elevated in Gabonese children with either uncomplicated malaria or CM, but not in Nigerian children with uncomplicated malaria." (PMID 24467887, 2014). "In light of the reported association with septic shock, our associations of elevated IL1R2, LCN2, LTF, MMP8, and OLMF4 in SM subtypes compared to uncomplicated controls may reflect a general signature of the inflammatory reaction to severe infection and may not represent a malaria-specific pathway." (PMID 40383794, 2025).
multiple sclerosis (9 papers, 2013 to 2023). A progressive autoimmune disorder affecting the central nervous system resulting in demyelination. "Several studies have shown that MMP8, also known as neutrophilic collagenase, is associated with neuroinflammatory diseases such as bacterial meningitis, spinal cord injury, and multiple sclerosis." (PMID 34803684, 2021). "MMP-8 which is predominantly produced by activated neutrophils and therefore called neutrophil collagenase, besides AS plays important pathogenic roles in other inflammatory autoimmune diseases like multiple sclerosis (MS) and RA." (PMID 36221125, 2022). "MMP-8 is an inducible MMP that has been shown to be upregulated in experimental models of multiple sclerosis and elevated in the CSF of children with bacterial meningitis." (PMID 29759062, 2018). "In contrast, Mmp8-deficient mice show reduced development of experimental autoimmune encephalomyelitis, suggesting that MMP-8 promotes pathology in this model of multiple sclerosis." (PMID 23632023, 2013). "MMP-8 was reported to play an important role in several pathological conditions, especially in inflammatory conditions such as heart disease, osteoarthritis, and multiple sclerosis." (PMID 35207175, 2022).
pneumonia (9 papers, 2012 to 2024). An acute, acute and chronic, or chronic inflammation focally or diffusely affecting the lung parenchyma, caused by an infection in one or both of the lungs (by bacteria, viruses, fungi, or mycoplasma.). "Potential mechanisms linking baseline levels of CRP, GDF-15 and MMP-8 to pneumonia risk require further study." (PMID 38105941, 2023). "Although the majority of deaths in this group of patients were due to pneumonia, separate cause-specific analyses revealed that MMP-8 levels were associated with mortality from both pneumonia and other forms of respiratory disease." (PMID 23031278, 2012). "Separate analyses of patients who had died from pneumonia or from other causes of respiratory disease demonstrated a significant association with MMP-8 levels in both cases, although the number of patients who had died from causes other than pneumonia was small (n = 13)." (PMID 23031278, 2012). "With regard to cytokine release and systemic inflammation IL-1RA, tenascin-C, and sCD163 increased from baseline to the day of pneumonia diagnosis, IL-6, IL-10, procalcitonin and sRAGE decreased, and IL-8, MMP-8, and sTREM-1 remained unchanged in cases." (PMID 37415223, 2023). "Further research on larger cohorts of patients will be needed to determine whether MMP-8 levels are predictive of mortality from specific respiratory diseases other than pneumonia." (PMID 23031278, 2012). "These patients also demonstrated a highly significant association of MMP-8 levels with mortality, similar to the total group who died from pneumonia (data not shown)." (PMID 23031278, 2012). "We have also confirmed in this second population that MMP-8 levels are associated with mortality from pneumonia, but this was independent of steroid use, which did not demonstrate a significant association (unpublished observations)." (PMID 23031278, 2012). "In addition to CRP, baseline GDF-15 and MMP-8 were also associated with future pneumonia risk independent of clinical comorbidities." (PMID 38105941, 2023). "In addition to observing multiple clinical variables associated with pneumonia, we identified 3 baseline serum protein immunoassay measures (GDF-15, MMP-8 and CRP), after adjusting for clinical variables, that were associated with pneumonia events up to 10 years prior to the pneumonia diagnosis." (PMID 38105941, 2023). "In a model adjusted for clinical variables, baseline GDF-15 (SHR, 1.32; 95% CI, 1.02–1.69), MMP-8 (SHR, 1.14; 95% CI, 1.01–1.30) and CRP (SHR, 1.16; 95% CI, 1.06–1.27) remained significant predictors of pneumonia." (PMID 38105941, 2023). "MMP-8 and MMP-9 levels are increased in patients with pneumonia, and this increase in lung tissue induces neutrophil influx, thereby contributing to the elimination of infectious agents." (PMID 36142454, 2022). "In particular, high circulating levels of MMP8 and MMP9 were found in patients affected by inflammatory conditions, such as pancreatitis and pneumonia." (PMID 23442769, 2013). "The top 50 over-abundant transcripts in pneumonia were dominated by antimicrobial neutrophil-related genes e.g ELANE, DEFA1B, MMP8, CAMP, DEFA3, DEFA4, MPO, LTF." (PMID 23940611, 2013). "Three baseline serum protein measurements were associated with pneumonia risk independent of measured clinical factors: growth differentiation factor 15 (SHR 1.32; CI 1.02–1.69), C-reactive protein (SHR 1.16, CI 1.06–1.27) and matrix metallopeptidase 8 (SHR 1.14, CI 1.01–1.30)." (PMID 38105941, 2023).
depression (8 papers, 2020 to 2025). "Pathway analysis and genome-wide association in major depressive disorder revealed a significant association with the MMP8 gene." (PMID 35215271, 2022). "These included several interesting candidates including TNFRSF17, previously reported to be significantly upregulated in women with PPD and MMP8, a matrix metalloproteinase gene, associated with depression in a genome-wide association study." (PMID 33664235, 2021). "The study identified elevated MMP8 as a key factor in depression and stress-related behavior changes, with its depletion reducing these effects, suggesting MMP8 as a potential therapeutic target." (PMID 40588528, 2025). "Behavioral deficits resembled those from major depressive disorder (MDD) raising the prospect of MMP8 as a new druggable target in tailored treatments." (PMID 38778067, 2024). "Circulating monocytes and monocytes that traffic to the brain showed increased expression of matrix metalloproteinase 8 (MMP8) both in patients with depression and in chronic stress models in mice." (PMID 39045550, 2024). "Given the availability of chemical MMP8 inhibitors, some of them in clinical trials, their usefulness in depression treatment should be considered." (PMID 38778067, 2024).
metabolic syndrome (8 papers, 2010 to 2025). A cluster of metabolic risk factors for CARDIOVASCULAR DISEASES and TYPE 2 DIABETES MELLITUS. "Studies have shown that MMP8 ispositively correlated with the components of metabolic syndrome, with higher MMP8levels associated with greater values in MetS components." (PMID 41523972, 2025). "Furthermore, MMP8, a gene involved ininflammation and tissue remodeling, has been identified as a risk factor forMetS, with its role in chronic inflammation and insulin resistance linking it tothe development of metabolic syndrome." (PMID 41523972, 2025). "Interestingly, similar to what we have found in our case, patients with metabolic syndrome also display increased circulating concentrations of pro-MMP-9, MMP-8, and TIMP-1, which were associated with increased concentrations of pro-inflammatory mediators and adhesion molecules." (PMID 20161799, 2010).
osteoarthritis (8 papers, 2016 to 2023). A noninflammatory degenerative joint disease occurring chiefly in older persons, characterized by degeneration of the articular cartilage, hypertrophy of bone at the margins and changes in the synovial membrane. "rs1940475 in the MMP8 gene was reported for its association with osteoarthritis, femoral head osteonecrosis, and bladder cancer in non-smokers." (PMID 35215271, 2022). "This disturbance in the lipid metabolism of chondrocytes is linked with pro-inflammatory events in osteoarthritis and in turn the biosynthesis of key players such as VEGF, MMP-13 and MMP-8, which regulate bone formation." (PMID 34830409, 2021). "MMP-8 is responsible for the increase in cytokines observed during inflammatory processes and MMP-13 participates in osteoarthritis, which is initiated by an inflammatory process." (PMID 34830409, 2021). "The study set out to determine the levels of metalloproteinases MMP-1, MMP-3 and MMP-8, as well as tissue inhibitor TIMP-1 in patients with osteoarthritis, following the administration of anti-rheumatic agents." (PMID 32185271, 2017). "MMP-8 is an enzyme, which degrades type I, II, III and IV collagen in bone and cartilage during development and bone remodeling and increases cytokines and initiates inflammation and osteoarthritis." (PMID 37240089, 2023).
bacterial meningitis (7 papers, 2009 to 2023). Inflammation of the membranes surrounding the brain and spinal cord due to a bacterial infection. "Previous research indicates that MMP-8 is a fundamental cause of blood-brain barrier (BBB) disruption and neuronal damage in human bacterial meningitis." (PMID 37901226, 2023). "CSF MMP-8 presented as an attractive prognostic marker in children with bacterial meningitis." (PMID 31780869, 2019). "The increase of MMP-8 is a specific feature of bacterial meningitis." (PMID 20442866, 2010). "Additionally there was a trend in our data to suggest that MMP-8, a collagenase principally derived from neutrophils and important in bacterial meningitis, might also be decreased by dexamethasone." (PMID 19789647, 2009). "We determined levels of MPO, MMP-8, MMP-9, and tissue inhibitor of metalloproteinase- (TIMP-) 1 in the CSF of children with bacterial meningitis and investigated how these inflammatory mediators relate to each other and to the disease outcomes." (PMID 31780869, 2019). "In particular MMP-8 and MMP-9 are upregulated in CSF of children with bacterial meningitis, levels being 10 to 1000-fold higher than in viral meningitis." (PMID 20442866, 2010). "Interestingly, MMP8 has been shown to facilitate blood brain barrier (BBB) disruption and increased permeability in bacterial meningitis by mediating proteolytic cleavage of the tight junction protein occludin, and detachment of human brain microvascular endothelial cells." (PMID 27050077, 2016).
Cirrhosis (7 papers, 2013 to 2024). A chronic disorder of the liver in which liver tissue becomes scarred and is partially replaced by regenerative nodules and fibrotic tissue resulting in loss of liver function. "After erlotinib treatment, expression of antifibrotic pathways, including Mmp2, Mmp3, and Mmp8, were enhanced in PCLS from CDAHFD-induced cirrhosis, while expression of profibrotic pathways, including Mmp9 and Mmp13, were hampered." (PMID 39445861, 2024). "Most liver cells have high levels of MMP-2, -3, -7, and -16 during viral hepatitis and HCC; MMP-8, -9, -10-, -12, -13, -14, and MMP-16 during HCC and cirrhosis; and MMP-24 during liver regeneration." (PMID 37509493, 2023). "QuantSeq 3′ mRNA sequencing revealed thirty-three downregulated genes associated with ECM after the NK cell treatment of CCl4-induced cirrhosis, including six MMP genes (MMP3, MMP8, MMP9, MMP11, MMP12, and MMP14)." (PMID 37189708, 2023).
hepatocellular carcinoma (7 papers, 2018 to 2022). A malignant tumor that arises from hepatocytes. "On the contrary, expression of MMP8 related positively to the expression of transforming growth factor β1 (TGF-β1) in hepatocellular carcinoma tissues, enhancement of which was related to cancer stage, metastasis and recurrence time." (PMID 35884594, 2022). "In hepatocellular carcinoma, high levels of MMP-8 and TIMP-1 have indicated poor survival, as did our levels in CRC." (PMID 29929486, 2018). "A high MMP-8 serum level predicts a worse prognosis in hepatocellular carcinoma." (PMID 35328734, 2022). "Many cancer drugs can decrease MMP8 levels along with other MMPs: The plant-based isoflavones genistein and glycitein, as well as the flavone apigenin, down-regulate MMP8 expression in vitro and inhibit leukemia cell invasion and decrease the viability of hepatocellular carcinoma cells." (PMID 31514474, 2019). "Moreover, in hepatocellular carcinoma, low serum MMP8 levels correlated with better overall survival." (PMID 31514474, 2019).
Insulin resistance (7 papers, 2020 to 2025). Increased resistance towards insulin, that is, diminished effectiveness of insulin in reducing blood glucose levels. "In previous studies, it was found that the expression level of MMP8 in obese patients is increased and that it can promote insulin resistance by cleaving insulin receptors." (PMID 33468174, 2021). "In this regard, MMP-8 can proteolytically modify insulin-receptor leading potentially to development of insulin resistance." (PMID 33375174, 2020). "Mechanistically, an in vitro study reported that human insulin receptor can be cleaved by MMP8 and this observation could explain, at least partly, the role of MMP8 in impaired insulin signaling and insulin resistance in obese individuals." (PMID 37445827, 2023). "The aim here was to study in overweight and obese women, typically manifesting with insulin resistance, whether IGFBP-1 and MMP-8 are related to and reflect systemic low-grade inflammation, metabolism and diet." (PMID 32923723, 2020).